MRAS (muscle RAS oncogene homolog)
Description:
Signal transducer in the Ras-MAPK signaling pathway that regulates cell proliferation and survival. Core component of the SHOC2-MRAS-PP1c (SMP) holophosphatase complex that regulates the MAPK pathway activation. The formation of the SMP complex only occurs when MRAS is GTP-bound. Unlike other Ras proteins, MRAS has low intrinsic GTPase activity and may require additional factors for activation. The SMP complex specifically dephosphorylates the inhibitory phosphorylation at 'Ser-259' of RAF1 kinase, 'Ser-365' of BRAF kinase and 'Ser-214' of ARAF kinase, stimulating their kinase activities. Recognized by LZTR1 that mediates its ubiquitination by a BCR (BTB-CUL3-RBX1) E3 ubiquitin-protein ligase complex.
Synonyms: RRAS3; M-RAs; R-RAS3; NS11
Tractability: Small molecule: a structure with a bound ligand is known. Antibody: UniProt places it where antibodies can reach, with high confidence; its Gene Ontology location is reachable by antibodies, with high confidence. PROTAC: its protein half-life has been measured.
Gene: Protein-coding gene on chromosome 3 (138,347,648 to 138,405,534, forward strand). Ensembl gene ENSG00000158186.
Subcellular location: Cell membrane
Subcellular location (Human Protein Atlas): Cytosol; Vesicles
Pathways (Reactome):
Disease: Gain-of-function MRAS complexes activate RAF signaling; SHOC2 M1731 mutant abolishes MRAS complex function
Signal Transduction: RAF activation
Gene Ontology:
Molecular function: GTP-dependent protein binding; GTPase activity; protein binding; G protein activity; GTP binding
Biological process: Ras protein signal transduction; actin cytoskeleton organization; establishment or maintenance of cell polarity; positive regulation of Ras protein signal transduction; positive regulation of TOR signaling; signal transduction
Cellular component: cytoplasm; protein phosphatase type 1 complex; plasma membrane; membrane
Genetic constraint (gnomAD): Loss-of-function variants: 4 observed, 20.62 expected, observed/expected ratio (o/e) 0.19, 90% interval 0.095 to 0.44. The upper end of that interval is the gene's LOEUF score, 0.44, which puts it in group 1 of 6, group 1 being the genes least tolerant of losing a copy. Missense variants: 154 observed, 271.4 expected, observed/expected ratio (o/e) 0.57, 90% interval 0.5 to 0.65. Synonymous variants: 98 observed, 105.7 expected, observed/expected ratio (o/e) 0.93, 90% interval 0.79 to 1.1.
Gene-disease validity (ClinGen):
ClinGen rates the evidence that MRAS causes each of these diseases.
Noonan syndrome (autosomal dominant): Moderate. Noonan Syndrome (NS) is characterized by short stature, typical facial dysmorphism and congenital heart defects.
Homologues: Orthologues: chimpanzee MRAS (100% identical), dog MRAS (100% identical), rabbit MRAS (100% identical), guinea pig MRAS (99% identical), rat Mras (98% identical), mouse Mras (97% identical), tropical clawed frog mras (92% identical), zebrafish mrasa (89% identical), zebrafish mrasb (86% identical), pig MRAS (81% identical), macaque MRAS (72% identical), Caenorhabditis elegans ras-2 (57% identical). Paralogues in human: RRAS2 (56% identical), RRAS (50% identical), KRAS (48% identical), HRAS (46% identical), NRAS (46% identical), RAP1A (46% identical), RAP1B (45% identical), RIT1 (43% identical), RALA (42% identical), RIT2 (41% identical), RALB (41% identical), RAP2B (40% identical), and 23 more.